CST3 (cystatin C)
Diseases named in the same sentence as CST3 in open-access papers (continued):
Sharing a sentence is not in itself a finding about the gene and the disease.
Sepsis (continued). "Regardless of the underlying precipitating factors, previous studies have demonstrated that cystatin C played a significant role in the diagnosis and prediction of kidney injury in sepsis or other critical clinical conditions." (PMID 36589822, 2022). "In the present study, elevated serum levels of creatinine, cystatin C, and BUN emphasized the renal injury associated with sepsis." (PMID 35884918, 2022). "In other studies of patients with a variety of disorders ranging from need of cardiac surgery, prior kidney diseases, sepsis and patients in the intensive care unit, P-cystatin C proved to be an earlier predictor of AKI, and our data supports these findings." (PMID 32824680, 2020). "In the full cohort, a multivariate logistic regression model adjusted for sepsis, age, sex, APACHE III score, AKI status, treatment arm, and LCA subphenotype showed that higher quartiles of cystatin C were strongly associated with 60-day mortality." (PMID 32653023, 2020). "In a study of 113 patients that were admitted to ICU with sepsis, cystatin C concentration was evaluated on days following admission and then compared with routinely assessed serum creatinine concentration." (PMID 31366007, 2019). "Cystatin C is documented to be a good marker of AKI in sepsis, allowing for prognosis 24 h before diagnosis." (PMID 31366007, 2019). "Creatinine and cystatin C levels measured in serum were significantly higher in the untreated sepsis group compared to the sham group (P<0.001) (Table-4)." (PMID 27622284, 2017). "Despite a constant production rate and secretion to the circulation, seemingly unaffected by sepsis, urinary cystatin C levels are amplified in septic patients." (PMID 25866432, 2015). "Impaired tubular reabsorption of middle-sized molecules, such as cystatin C, during sepsis is one likely explanation to this phenomenon." (PMID 25866432, 2015). "At the time of enrolment, serum concentrations of creatinine and cystatin C were similar in neonates with sepsis, severe sepsis, and the control group." (PMID 24579085, 2014). "In this study urinary cystatin C was independently associated with AKI, sepsis, and death within 30 days." (PMID 23476755, 2013). "In a study of 444 ICU patients concentrations of urinary cystatin C were significantly higher in the presence of sepsis or AKI." (PMID 23476755, 2013). "Univariate analysis revealed that RDW (OR=1.947), APACHE II score (OR=2.303), PCT (OR=1.423), IL-6 (OR=1.237), CRP (OR=1.212), cystatin C (OR=1.324), and the main source of infection (OR=1.478) were significantly associated with the development of AKI in children with sepsis." (PMID 41281283, 2025). "The development of AKI in sepsis patients was strongly associated with RDW, APACHE II score, and the biomarkers PCT, IL-6, CRP, and cystatin C. After the intervention, the incidence of AKI and AKI grade 3 significantly decreased, along with lower rates of renal replacement therapy and mortality." (PMID 41281283, 2025). "Our findings also revealed that levels of apolipoprotein A, total cholesterol, and transferrin were significantly decreased in sepsis patients, while levels of cystatin C, rheumatoid factor, TIBC, CA19-9, ESR, PSA, CA125, tPSA, and hydroxybutyrate dehydrogenase were markedly elevated." (PMID 38835774, 2024). "Elevated cystatin C levels indicate reduced renal function, a common complication in sepsis." (PMID 38835774, 2024). "However, there is a lack of information about the analysis and use of other possible biomarkers of sepsis, such as Cystatin C, ammonia, and bicarbonate, in the saliva of pigs." (PMID 38891627, 2024). "The areas under the receiver operating curves demonstrated that serum cystatin C had modest discriminative powers for predicting AKI after sepsis, and cystatin C combined with serum creatinine in the prediction of septic AKI increased the diagnostic sensitivity prominently." (PMID 35272698, 2022).
Sepsis (continued). "Horses that were determined to be at risk for AKI (with colic but without endotoxemia, sepsis or systemic inflammatory response syndrome, and with absence of azotemia) were shown to have elevated serum and urine cystatin C concentrations." (PMID 36230418, 2022). "Acceleration of autophagy improves renal function, as monitored by serum cystatin C. These results suggest that autophagy plays a protective role against sepsis-induced kidney injury and may mitigate other physiological abnormalities during sepsis as well." (PMID 29348412, 2018). "However, the superiority of Cystatin C over SCr for GFR estimation in critical illness, as well as the impact of inflammation and sepsis on cystatin C levels, is doubtful." (PMID 28657585, 2017). "In addition, cystatin C and creatinine levels were significantly lower in the groups receiving 5 and 10mg/kg tadalafil than in the untreated sepsis group (p<0.001)." (PMID 27622284, 2017). "In addition, we observed an independent association between sepsis and higher NGAL and cystatin C concentrations in urine." (PMID 25866432, 2015). "In the present study, pCysC was not independently associated with sepsis, suggesting that excess filtration of cystatin C (overload proteinuria) was not responsible for the increase in uCysC." (PMID 20459852, 2010). "Urinary cystatin C was independently associated with AKI, sepsis, and death within 30 days." (PMID 20459852, 2010). "• In the ICU, urinary cystatin C predicts AKI in the presence of sepsis." (PMID 20459852, 2010). "And some studies reported that severe systemic inflammation caused by sepsis could lead to the elevation of cystatin C, so the prediction of cystatin C in septic AKI is negative." (PMID 35272698, 2022). "Therefore, cystatin C or its regulation may be an interesting candidate for treatment of disorders with excessive inflammation, such as sepsis, Crohn’s disease or neurodegenerative disorders." (PMID 34440840, 2021). "Cystatin C levels varied significantly across the different TNF-α (−238, rs361525) genotypes among critically ill patients with sepsis." (PMID 40724987, 2025). "This study was designed to assess the value of serum cystatin-C levels and genetic determinants, such as TNF-α (−238, rs361525), for predicting and diagnosing S-AKI development in critically ill patients with sepsis." (PMID 40724987, 2025). "In this study, we developed a simple nomogram model (based on MAP, PLT, Cystatin C, HDL, and apoE) to predict MAKE30 in sepsis patients with T2DM." (PMID 36589822, 2022). "We constructed a simple nomogram model to predict MAKE30 in sepsis patients with T2DM based on those independent predictors (MAP, PLT, Cystatin C, HDL, and apoE) within 24 hours of admission." (PMID 36589822, 2022). "The cut-off value for cystatin C in predicting AKI was 10.4 μg/ml, sensitivity and specificity values of cystatin C in predicting AKI in sepsis patients were 0.767 and 0.802." (PMID 35272698, 2022). "The application of the nomogram model is demonstrated by the following example: assuming a sepsis patient with T2DM with a MAP of 70 mmHg, a Cystatin C of 3 mg/L, an HDL of 1 mmol/L, a PLT of 200 x 109/L, and an apoE of 40 mg/L." (PMID 36589822, 2022). "In sepsis patients with T2DM, Mean Arterial Pressure (MAP), Platelet (PLT), cystatin C, High-Density Lipoprotein (HDL), and apolipoprotein E (apoE) were independent predictors for MAKE30." (PMID 36589822, 2022). "Then, it revealed that in sepsis patients with T2DM, MAP (0.928,0.906-0.950), PLT (0.995,0.992-0.999), HDL (0.009,0.002-0.036), apoE (0.988,0.979-0.997), and cystatin C (1.960,0.360-2.826) were independent predictors for MAKE30." (PMID 36589822, 2022). "In conclusion, our study demonstrated that in sepsis patients with T2DM, the levels of MAP, PLT, Cystatin C, HDL, and apoE available within 24 hours after admission played a critical role in MAKE30 prediction." (PMID 36589822, 2022).
Sepsis (continued). "CLP sepsis also impaired renal function as indicated by elevation of BUN, creatinine, and cystatin C in the control group 24 h after CLP." (PMID 34045461, 2021). "Serum cystatin C has been evaluated as a marker of AKI in various settings, including sepsis and AP." (PMID 31940861, 2020). "As such, serum cystatin C detects AKI early and better reflects inulin GFR in cecal ligation and puncture (CLP)-induced murine sepsis." (PMID 28430696, 2017). "On the other hand, higher cystatin C level was an independent predictor of mortality in the ICU, when adjusted by age, gender, APACHE II score, vasopressors, sepsis, ICU hospitalization days, and serum albumin level." (PMID 24967238, 2013). "Using NGAL as the dependent variable, the presence of sepsis, the renal variables from the SOFA score, CRP, and serum cystatin C were independently related to NGAL levels at initiation of RRT." (PMID 20122150, 2010). "Elevated serum NGAL is independently related to the severity of AKI (cystatin C and renal SOFA), but also to the presence of sepsis and the extent of systemic inflammation (CRP)." (PMID 20122150, 2010). "Cystatin C, ammonia, and bicarbonate have been reported to be biomarkers of sepsis and inflammation in humans, but there is a lack of information about assays for the measurement of these analytes in pigs." (PMID 38891627, 2024). "In addition, we demonstrated that in sepsis patients with T2DM, cystatin C was an independent predictor of MAKE30." (PMID 36589822, 2022). "The data presented here reveal a protective role of cystatin C in LPS-induced sepsis and NLRP3 inflammasome activation that is independent of protease inhibition." (PMID 34440840, 2021). "A panel consisting of A2ML1, CD14, CST3, PEDF, RET4, and VASN produced an area under the curve (AUC) of 98.4% for distinguishing medical and surgical NEC, and a panel consisting of CST3, PEDF, and RET4 produced an AUC of 98.2% for distinguishing NEC from sepsis." (PMID 31178908, 2019). "As with serum creatinine, sepsis decreases serum cystatin C production and increases nonrenal clearance." (PMID 28430696, 2017). "Septic patients, as compared to non-septic patients, had higher plasma NGAL at inclusion (P < 0.001), whereas endostatin (P = 0.09) and cystatin C (P = 0.08) levels were similar in patients with and without sepsis." (PMID 26762504, 2016). "However, there is a lack of assays for the possible measurement and use of cystatin C, ammonia, and bicarbonate in saliva as biomarkers of sepsis or inflammation in pigs." (PMID 38891627, 2024). "Therefore, a multi-marker approach including u-actin and the measurement of various damage biomarkers (e.g. urine Cystatin C, KIM-1, NGAL, IL-18) may provide valuable information regarding the more accurate staging of sepsis-related AKI." (PMID 34310652, 2021). "Although serum creatinine and cystatin C were elevated in CLP mice in comparison to naive mice, significant increases were seen only in moderately-to-severely septic mice (MSS of 7–12 and 13+, respectively), and not in mice with mild sepsis (MSS ≤ 4), which represent the early stage of sepsis." (PMID 32669536, 2020). "This may mean different thresholds in different cohorts, such as for urinary Cystatin C or NGAL in sepsis, as well as recognising that the kidney injury “signal” may be drowned out by other sources of the biomarker in some circumstances, thus rendering the biomarker not diagnostic of Structural-AKI." (PMID 23626850, 2013). "Cystatin C production is constant, and its variations are almost independent of sepsis." (PMID 20546598, 2010). "Therefore, we performed a prospective study with sepsis patients in order to explore early biomarkers for AKI prediction at hospital admission and these biomarkers included measurements of glomerular function (cystatin C), proximal and distal tubule function (KIM-1 and klotho)." (PMID 35272698, 2022).
atherosclerosis (53 papers, 2011 to 2026). A disease characterized by the build-up of fatty material and calcium deposition in the arterial wall resulting in partial or complete occlusion of the arterial lumen. "In contrast, CST3 B, an allele of cystatin C, often leads to a decrease in cystatin C secretion, which ultimately leads to the development of atherosclerosis." (PMID 38845616, 2024). "Meanwhile, a high Cystatin C concentration is associated with inflammation and endothelial dysfunction, which is involved in the pathogenesis of atherosclerosis." (PMID 35711907, 2022). "Later studies found that inflammatory cells and cytokines associated with atherosclerosis can stimulate the production of lysosomal cathepsins, and increase plasma concentrations of cystatin C." (PMID 35392813, 2022). "We have previously identified novel interactions between eQTL and clinical traits in the DO, including atherosclerosis, the atherosclerosis-associated plasma metabolite trimethylamine N-oxide, and plasma cystatin C." (PMID 34849860, 2021). "Cystatin C has been proposed to be not only a sensitive marker of kidney dysfunction but also a biomarker of atherosclerosis and cardiovascular risk." (PMID 32306911, 2020). "This contributes to the development of atherosclerosis and cardiovascular disease and explains why cystatin C is the renal biomarker that presents a better association with hypercoagulability status." (PMID 29694626, 2018). "EAT accumulation and elevated cystatin C have been independently regarded as risk factors influencing atherosclerosis." (PMID 28922364, 2017). "EAT accumulation and a high cystatin C concentration have been independently regarded as risk factors influencing atherosclerosis." (PMID 28922364, 2017). "Expression of cystatin C (CysC) is decreased in human atheroma, and CysC deficiency enhances atherosclerosis in mice." (PMID 27079462, 2016). "Then, we investigated the association between cystatin C and other biochemical risk factors for atherosclerosis." (PMID 22978689, 2012). "Elevated cystatin C levels are indicative of impaired renal function, and chronic kidney dysfunction is associated with oxidative stress and systemic inflammation, which accelerate atherosclerosis." (PMID 40941489, 2025). "Moreover, cystatin C is a known inhibitor of cysteine proteases such as cathepsins, which have been implicated in the development of atherosclerosis." (PMID 40983592, 2025). "Many studies have reported that cystatin C is associated with atherosclerosis." (PMID 39969384, 2024). "Cystatin C may associated with the destabilization and rupture of coronary artery plaque in the pathological processes of atherosclerosis, which were account for the high risk of cardiovascular events in highest cystatin C quartile." (PMID 37817071, 2023). "A potential mechanism is that inflammatory cytokines associated with atherosclerosis may alter the relationship between cysteine protease and their endogenous inhibitor cystatin C." (PMID 35883416, 2022). "Interestingly, cystatin C showed associations with the parameters related to metabolic syndrome and with the surrogate markers of atherosclerosis." (PMID 28922364, 2017). "The aim of this study was to investigate the role of cystatin C level as a predictor of cardiovascular events and the association between this protein, oxidative stress markers, and other biochemical risk factors for atherosclerosis in patients with CAD." (PMID 24478035, 2014). "Cystatin C is associated with biochemical atherosclerosis markers such as CRP and homocysteine." (PMID 24478035, 2014). "In addition to the association with atherosclerosis, connections between cystatin C and features of the MetS have also been illustrated by a few recently published studies." (PMID 22978689, 2012). "As cystatin C is a cardiovascular risk marker, this study may implicate that longer time periods of immobilization augment the risk of atherosclerosis." (PMID 22152087, 2011).
atherosclerosis (continued). "Increases in cystatin C concentrations directly damage endothelial cells, thereby reducing nitric oxide production, altering coagulation factor function, promoting platelet adhesion and aggregation, and causing thrombosis, thereby participating in the occurrence and development of atherosclerosis." (PMID 37663661, 2023). "In addition, cluster 0 expressed Serpinf1, involved in ossification and osteoblast differentiation, Hsd11b1, shown to exacerbate atherosclerosis, Pex5l, expressed in macrophages and Gfra2 in monocytes, as well as cystatin C, associated with coronary artery calcification." (PMID 35163719, 2022). "Thus, this study evaluated whether independent cross-sectional associations existed between urinary ACR and cystatin C with subclinical atherosclerosis in participants of the Taichung Community Health Study (TCHS)." (PMID 33129312, 2020). "Inflammatory cytokines associated with atherosclerosis stimulate the production of lysosomal cathepsins, and increased plasma concentrations of cystatin C, a cathepsin inhibitor, may reflect, at least in part, an attempt to counterbalance a potentially damaging increased elastolytic activity." (PMID 24478035, 2014). "Our finding might reflect that bed rest increases inflammatory activity, which in turn advances the atherosclerotic process leading to enhanced risk of CVD as well as elevated cystatin C levels by atherosclerosis in the kidneys and thereby a decreased glomerular filtration rate." (PMID 22152087, 2011). "Inflammatory cytokines associated with atherosclerosis stimulate the production of lysosomal cathepsins and increase the plasma concentration of cystatin C. Cystatin C is a cathepsin inhibitor and might therefore play a roll in counterbalancing a potentially destructive greater elastolytic activity." (PMID 22152087, 2011). "The MAF-5 score is a non-invasive prognostic marker of liver fibrosis and mortality, while Cystatin C (CysC) is a sensitive indicator of renal function that also reflects inflammation, atherosclerosis, and metabolic dysfunction." (PMID 41590679, 2026). "High cystatin C concentration was found to be involved in inflammation, which promotes atherosclerosis." (PMID 37155257, 2023). "Cystatin C can also accelerate the development of atherosclerosis by regulating the activity of cysteine protein kinase to balance the production and degradation of the extracellular matrix." (PMID 37663661, 2023). "This study indicated that CST3 in the XXZ group of acute ischemic stroke patients was mainly associated with “response to lipid,” aligning with previous studies linking Cys C to atherosclerosis." (PMID 38090270, 2023). "Cystatin C, as an inhibitor of cysteine proteases, plays an important role in the pathogenesis of atherosclerosis." (PMID 35585568, 2022). "Ian H de Boer reported that increased cystatin C concentrations were associated with greater TG and HDL-C concentrations in the multi-ethnic study of atherosclerosis." (PMID 36506069, 2022). "Cystatin C and ACR were strongly and linearly associated with carotid thickening, a marker of subclinical atherosclerosis." (PMID 33129312, 2020). "Our study supported previous results, which indicated that cystatin C can be used as a precise indicator to help the early diagnosis of atherosclerosis in community-based adults." (PMID 33129312, 2020). "In this study, elevated serum cystatin C showed a simple correlation with surrogate markers of atherosclerosis, such as max IMT, baPWV and CACS, while these relationships disappeared with adjustment for age on multiple regression analysis." (PMID 28922364, 2017). "It has been proposed that elevated cystatin C levels are directly correlated to both inflammation and atherosclerosis." (PMID 22152087, 2011). "From the Women International Space simulation for Exploration study (WISE) we studied markers of atherosclerosis and kidney function, including cystatin C, in a standardized bed rest study on healthy volunteers." (PMID 22152087, 2011).